MYCN (MYCN proto-oncogene, bHLH transcription factor)
Diseases named in the same sentence as MYCN in open-access papers (continued):
Sharing a sentence is not in itself a finding about the gene and the disease.
tumor (continued). "MYCN directly modulates immune cell infiltration to the TME by altering cytokine production in NBL tumor cells." (PMID 37426669, 2023). "The mechanism by which macrophages infiltrated the TME was through the increase in colony-stimulating factor (CSF1) and chemokine ligand 2 (CCL2) (both involved in macrophage recruitment) in post-treatment MYCN-amplified tumours." (PMID 37887559, 2023). "Since the effects of GSK2801 on in vitro tumor aggressiveness, we repeated the analysis after MYCN inhibition by VPC-70619." (PMID 36983070, 2023). "SOX11 was identified as the sole protein coding gene residing in the shortest region of overlap at 2 p distal to MYCN, suggesting a role as driver for selection of the respective amplicons during tumor formation." (PMID 36882421, 2023). "This is just considered to be an initiating event, and studies are still going on the development of MYCN amplified tumours." (PMID 37667345, 2023). "MYCN amplification in NB presents as double minutes (DMs) in 93% of tumour cases, HSRs in 6%, and DMs and HSRs together in <1%." (PMID 37958407, 2023). "MYCN, a proto-oncogenic transcription factor, fosters tumor cell proliferation, angiogenesis, and metastasis, concurrently suppressing immune activation." (PMID 38087370, 2023). "In particular, miR-34a is the most extensively studied miRNA that directly regulates MYCN expression and acts as a tumor suppressor by inducing NB cell apoptosis." (PMID 38069407, 2023). "The authors previously showed that overexpression of LIM-domain-only 1 (LMO1), a transcriptional coregulator, synergizes with MYCN to accelerate tumor formation and metastasis in an NBL-zebrafish model." (PMID 37183823, 2023). "Previous studies have demonstrated the direct contribution of MRP1 to tumor responsiveness to chemotherapy in a MYCN amplified NB." (PMID 36874032, 2023). "We will also discuss the emergence of the Aurora-A and -B protein kinases, their unique contribution to the aggressiveness of MYCN-amplified tumours, and underappreciated regulation of cellular bioenergetics." (PMID 37414143, 2023). "After assessing the levels of gene expression reduction (Log2), their cellular function, basal expression levels, and grade of relevance in involvement in tumor, we chose MYCN as an important gene whose expression is reduced in both cell lines." (PMID 36983070, 2023). "This transitional cell subpopulation expressed markers such as MYCN, EZH2, and SOX11 and was associated with rapid proliferation and tumour metastasis." (PMID 37887559, 2023). "On the other hand, in the in vivo evaluation with intratumoral injection, 191Pt-MYCN-PIP was up-taken into tumor cells and bound to DNA." (PMID 38004392, 2023). "MYCN has been shown to bind to numerous promoters and CpG islands (CGIs) in NB, suggesting direct control of potential tumor suppressor genes via DNA methylation." (PMID 38069407, 2023). "With our model, we are presenting a second tumorigenic hit, which allows tumor formation with a wild-type MYCN, possibly by transcriptional or epigenetic changes allowing the accumulation of MYCN in the cells." (PMID 37407554, 2023). "The tumor growth patterns in later stage are consistent with that in early stage and depletion of BAP1 in BE2C cells markedly retarded tumor growth and overexpression of MYCN in shBAP1 cells dramatically increased the tumor growth." (PMID 37543638, 2023). "The methylation levels of CENPA and TIMP1 were downregulated in tumor tissues, while MYCN, in contrast to them, had elevated methylation levels." (PMID 37213288, 2023). "Spinal ependymoma MYCN-amplified harbors a distinct DNA methylation profile and, by definition, MYCN amplification in tumor cells." (PMID 38074692, 2023). "Among them, the miRNAs miR-34b-3p, miR-29a-3p, miR-34c-5p, and miR-29b-3p appear upregulated in PDX5, and one of their possible targets is the oncogene MYCN mRNA, which is highly maintained over the passages, as the original tumor is NMYC-amplified." (PMID 36675105, 2023).
tumor (continued). "In another MYCN driven tumor, RMS, MYCN binds to enhancers and directly represses muscle differentiation genes, suggesting a general mechanism by which enhancer-bound MYCN represses differentiation genes." (PMID 37781575, 2023). "Tumor histology, the MYCN oncogene status, tumor cell DNA content as well as genetic markers, like 11q or 1p deletions are well known prognostic factors." (PMID 36865795, 2023). "The prognosis of the disease varies with age, tumor grade, and various biological features, as well as amplification of the MYCN (MYCN Proto-Oncogene, BHLH Transcription Factor) oncogene." (PMID 37370314, 2023). "MYCN has several critical functions encompassing cell cycle regulation, cell growth and proliferation, tumor cell angiogenesis, and metastasis." (PMID 37046804, 2023). "We have developed a compound WS6 and its analogous, which inhibits PA2G4 and MYCN protein levels and reduces tumour cell growth." (PMID 36980710, 2023). "In cultures from hGFAP-cre::CrebbpFl/Fl::lsl-MYCN tumor cells (n = 3) the number of viable cells increased over time, as demonstrated by a corresponding CellTiter-Glo® Luminescent Cell Viability in vitro assay." (PMID 37407554, 2023). "One study showed that most high-risk NB tumours have TERT rearrangements, MYCN amplification or ATRX mutations, all of which extend telomere length, suggesting an important role for TMM in clinical prognosis." (PMID 37958407, 2023). "We profiled CNAs in the tumor tissues for further evaluation of alterations in 1q, MYCN and 17p in the circulating tumor DNA (ctDNA) in the peripheral blood at diagnosis and follow-up using digital PCR." (PMID 37189699, 2023). "NB is grouped into three risk groups, low, intermediate and high, on the basis of clinical (age and tumour spread) and biological features (including the presence of MYCN oncogene amplification) with treatment varying accordingly." (PMID 37958407, 2023). "In MNA NB, MYCN is known to be predominantly a repressor of tumor suppressor miRNA expression, although several miRNAs, including the miR-17-92 cluster, were found to correlate with MYCN expression." (PMID 38069407, 2023). "These ncRNAs can also directly target the 3’ untranslated region (3’UTR) of MYCN mRNA or act via indirect pathways to influence tumor progression." (PMID 38069407, 2023). "Comparing data from the SK-N-AS cell model with induced MYCN expression and MYCN-amplified tumor samples detected 4253 commonly expressed circRNAs." (PMID 37402719, 2023). "One third of advanced NB tumours have MYCN oncogene amplification and overexpression, which predicts poor patient prognosis." (PMID 36980710, 2023). "In subcutaneous (s.c.)xenografts, IGF2BP1-KO impaired tumor engraftment, MYCN expression and delayed growth by 5–7 days." (PMID 37246217, 2023). "Although MYC or MYCN must be involved in the tumor initiation process, we found that the MYC/MYCN pathway is suppressed in ArfARF-depleted HGG-like tumors." (PMID 36869047, 2023). "Deregulation of the MYC family of transcription factors c-MYC (encoded by MYC), MYCN, and MYCL is prevalent in most human cancers, with an impact on tumor initiation and progression, as well as response to therapy." (PMID 37760568, 2023). "Targeting the cofactors that mediate these two pathways antagonizes the dysregulated MYCN activity and more effectively suppresses NB tumor cell growth." (PMID 37781575, 2023). "This 9464D tumor model is MYCN-driven and can be implanted for growth in syngeneic immunocompetent C57Bl/6 mice." (PMID 37835389, 2023). "Other miRNAs such as miR-15a-5p, miR-15b-5p, miR-16-5p, miR-101, miR-628-3p, and let-7 inhibit tumor progression by negatively affecting MYCN expression." (PMID 38069407, 2023).
tumor (continued). "With the aim to further investigate characteristics of the tumor cells, we isolated and dissociated OB cells of 3- to 4-week-old hGFAP-cre::CrebbpFl/Fl::lsl-MYCN mice and their CrebbpFl/Fl::lsl-MYCN littermates." (PMID 37407554, 2023). "MYCN oncogene amplification is detected in 25% of NB patients and is a known marker of tumor aggressiveness." (PMID 38012558, 2023). "Still, MYC was able to rescue these MYCN-suppressed cells and became the key driver of proliferation, leading to complete rescue and survival of tumor cells." (PMID 36869047, 2023). "The expression of MYCN and CDKN2A was associated with tumor stage, metastasis, and overall survival in our cohort." (PMID 37878133, 2023). "Several small-molecule inhibitors have successfully disrupted the interaction between N-MYC and AURKA, leading to the destabilization and degradation of N-MYC and subsequently tumor regression in MYCN amplified cancers." (PMID 36830089, 2023). "Extensive evidence, from our lab and others, have shown that MYCN-BPs can markedly increase MYCN protein stability to drive tumour formation." (PMID 36980710, 2023). "Previously, we demonstrated that a ketogenic diet (KD) combined with metronomic cyclophosphamide (CP) delayed tumor growth in MYCN-amplified NB xenografts." (PMID 37623854, 2023). "CREBBP and MYCN stainings of OBs of P21 mice confirmed strong accumulation of MYCN and loss of CREBBP in tumor tissue compared to the control." (PMID 37407554, 2023). "Given the tight relationship between MYCN amplification status and tumor stage, it is unclear which factor is responsible for the correlation between MYCN amplification and TIL infiltration." (PMID 37239815, 2023). "We have demonstrated that high expression of USP7 is associated with poor prognosis in children with NB and with other biological features of poor prognosis such as MYCN amplification and increased tumor stage." (PMID 37762082, 2023). "Extensive evidence from us and other researchers has shown that some MYCN binding proteins markedly increase MYCN protein stability to drive tumour formation." (PMID 36980710, 2023). "The youngest patient was four months old at diagnosis and was classified as having INSS stage 4S, but had an MYCN-amplified tumor." (PMID 38136138, 2023). "We have demonstrated that LMO1 overexpression synergizes with MYCN to accelerate tumor onset, penetrance, and metastasis in a dβh:MYCN- driven zebrafish model." (PMID 37183825, 2023). "The authors revealed that MYCN-driven mouse tumours are low in T cells but higher in macrophage, MSDC, and CAF content, corresponding with an overall immunosuppressive environment." (PMID 37887559, 2023). "In an immunocompetent mouse model, Th-MYCN treatment with copper-chelating drugs enhanced tumor proliferation and survival." (PMID 37007132, 2023). "hGFAP-cre::CrebbpFl/Fl::lsl-MYCN mice thus provide a valuable tool to study tumor-driving mechanisms in a key neural stem/ progenitor cell niche." (PMID 37407554, 2023). "Taken together, ONC201 achieves the significant tumor inhibitory effect through interrupting the mitochondria function and modulating the expression of ATRX and MYCN, the two critical clinical risk factors for patients with NB." (PMID 36675163, 2023). "The colony and tumour sphere formation ability of MYCN‐AM NB cells re‐expressed M4 mutant was significantly diminished compared to those transfected with CCNB1IP1 WT." (PMID 37461251, 2023). "The inactivation of MYCN will promote the apoptosis of cancer cells, thus inhibiting the development of tumor." (PMID 37878133, 2023). "In all, 11 variables, namely age, race, gender, tumor grade, INSS stage, tumor site, histological type, COG risk group, MYCN gene status, DNA ploidy, and MKI, were analyzed in the univariate Cox analysis, and the KM curves were plotted." (PMID 37746942, 2023). "ARV-825 is a PROTAC bromodomain inhibitor that exerts anti-tumour activity by inhibiting the expression of MYCN or c-Myc." (PMID 37957420, 2023).
tumor (continued). "The representative prognostic variables are stage, age at diagnosis, MYCN oncogene status, chromosome 11q status, DNA ploidy, and the histological category and grade of tumor differentiation." (PMID 36831211, 2023). "TEAD4 is up-regulated in a variety of tumors and is a potential tumor prognostic marker, especially in MYCN-amplified NB cells, and is a key component to drive their proliferation." (PMID 36770809, 2023). "The prognosis of NB patients varies widely, depending on the age of the child, the tumor grade at diagnosis, and various molecular pathological features, especially the amplification of the MYCN oncogene." (PMID 36874032, 2023). "Previous studies suggests that the combination of DAC and ATRA synergistically induces apoptosis, growth inhibition, and differentiation of AML cells by inducing the expression of anti-tumour genes and modulating the miR-34a/MYCN axis in vitro." (PMID 36482192, 2023). "Mechanistically, MYCN is proposed to rewire metabolism to enable NB tumor cells to proliferate, in turn preserving the intracellular redox balance while producing enough energy by inducing a glycolytic switch." (PMID 35379801, 2022). "In this light, the central role of MYCN in NB pathogenesis emerges also in the cancer-initiating phases through the regulation of the cell division fate, not only in tumor progression." (PMID 35277192, 2022). "As expected, administration of DZNep depleted MYCN (and Ezh2) concomitantly with a dramatic inhibition of primary tumor cell growth in vitro, whereas the enzymatic inhibitor GSK126 exhibited minimal effects." (PMID 35013218, 2022). "Increased expression of MRN genes has been observed in MYCN‐driven tumours and other cancer types, including prostate, gastric, rectal and head‐and‐neck cancers." (PMID 35839783, 2022). "On the other hand, the MRN complex also exerts oncopromoting functions and confers survival advantages to tumour cells by facilitating resistance to oncogene‐induced RS, as demonstrated for MYCN‐driven neuroblastoma and c‐MYC‐driven B‐cell lymphomas." (PMID 35839783, 2022). "Specifically, cytogenetic factors, MYCN amplification status and chromosome aberrations of 1p and 11q, are chosen as representative indicators of tumor biology." (PMID 35372427, 2022). "Tumor stages, age at diagnosis, histology category, tumor differentiation, and MYCN status are the major factors of INRG classification schema." (PMID 35846139, 2022). "For example, FDG uptake was significantly higher in the MYCN-amplified tumor (SUVmax: 7.9, 95% CI: 6.7–9.9 vs. 5.1, 95% CI: 4.9–6.6, p < 0.001, adjusted p = 0.005)." (PMID 36353561, 2022). "A characteristic feature of the model was an increase in bone marrow metastasis, as compared with animals over-expressing MYCN with wild-type levels of CASP8 (although primary tumor formation was unaffected)." (PMID 36231134, 2022). "The formulation enhanced oxidative stress and triggered caspase-dependent apoptosis targeted to MYCN-amplified tumor cells and sparing non-MYCN augmented populations." (PMID 35055257, 2022). "SLC27A2 is necessary for NB survival, as both genetic interference and pharmacological inhibition via the small-molecule inhibitor CB5 impaired MYCN-induced tumor growth." (PMID 35764645, 2022). "This indicated that MYCN amplification status, tumor stage and age at diagnosis each influenced the prognostic value of high EIF4EBP1 expression in the SEQC and NRC cohorts." (PMID 35379801, 2022). "The Children's Oncology Group (COG) has applied disease stage, age at diagnosis, MYCN status, tumor histology, and DNA index to stratify patients' prognostic risk." (PMID 35315591, 2022).
tumor (continued). "Although apparently counterintuitive, the idea that NBS1 is necessary for MB development is consistent with the previous data indicating that the MRN complex is required to control MYCN‐dependent RS and DNA damage in primary GCPs and in MYCN‐dependent tumours." (PMID 35839783, 2022). "Existing studies of PARP inhibition in NB have largely established its efficacy in specific tumor types, including those that amplify or overexpress MYCN, as well as those with 11q deletion and/or low ataxia-telangiectasia mutated (ATM) expression." (PMID 36227363, 2022). "Previous studies have found that N-myc in MYCN positive tumor cells abnormally regulates G1/S checkpoint, inhibits G1 arrest after DNA damage, promotes tumor cells to enter the S phase with DNA damage repairing and experiencing chronic replication stress." (PMID 36311753, 2022). "Collectively, our data suggest that blocking MYCN-induced metabolic reprogramming effectively enhances the anti-tumor effects of conventional chemotherapy." (PMID 35764645, 2022). "Evidence demonstrated that when expressed at deregulated levels, MYCN invades enhancers to drive tumor-specific processes in NB." (PMID 35277192, 2022). "MYCN amplification impact is not limited to the cancer cell itself but also to the tumor microenvironment." (PMID 36139583, 2022). "MYCN is a strong driver of NB tumorigenesis, as tissue-specific overexpression of MYCN is sufficient to induce NB tumor development in mouse models." (PMID 35379801, 2022). "Due to the significant role of MYCN in NB and some other tumor types, together with the fact that it is overexpressed in tumors but not in normal tissue, MYCN represents a good therapeutic target." (PMID 36505784, 2022). "Morscher and colleagues observed a greater inhibition of tumor expansion in MYCN-amplified mCTX-treated xenografts, as well as a considerable diminution of blood vessel density and intratumoral bleeding." (PMID 36362482, 2022). "Addition of MG132 consistently rescued the MYCN loss caused by EZH2 depletion in NCI-H526 cells, arguing that EZH2 regulates MYCN stabilization in these tumor cells." (PMID 35013218, 2022). "Our analysis also elaborated the transcriptional signature of panobinostat in order to identify which gene networks were most affected by the drug, finding TFs previously unassociated with NBL and confirming the central role of MYCN in NBL tumor sustenance." (PMID 36553506, 2022). "The increased vulnerability of the MYCN-amplified cells compared to tumor cells with normal MYCN levels was explained by high-level transcription from super-enhancer associated-MYCN and other genes with increased Pol II activity." (PMID 35681734, 2022). "To evaluate the role of MYCN 3’UTR-mediated signals in contributing to the anticancer activity of MX25-1, we examined the status and activation of the tumor suppressor microRNA (miRNA) let-7, which is a target of MYCN 3’UTR in MYCN-amplified NB." (PMID 36505784, 2022). "Here, we report that EIF4EBP1 expression levels are significantly elevated in NB compared to corresponding non-tumor tissues and positively correlate with both MYCN expression and MYCN amplification status in at least two independent NB patient cohorts." (PMID 35379801, 2022). "The COG has applied disease stage, age at diagnosis, MYCN status, tumor histology, and DNA index to stratify patients' prognostic risk." (PMID 35315591, 2022). "Such therapy would both inhibit MYCN’s cell-survival effects and activate the tumor-suppressor effect of let-7." (PMID 36505784, 2022). "Inhibition of FAO by small-molecule inhibitors that target CPT1C reduces the survival of MYCN-amplified cells in vitro and attenuates tumor growth in vivo." (PMID 36077650, 2022).